LSG1 (large 60S subunit nuclear export GTPase 1)
Description:
Functions as a GTPase. May act by mediating the release of NMD3 from the 60S ribosomal subunit after export into the cytoplasm during the 60S ribosomal subunit maturation.
Synonyms: FLJ11301
Tractability: PROTAC: ubiquitination databases record sites on it; its protein half-life has been measured.
Target class: Enzyme; Hydrolase
Gene: Protein-coding gene on chromosome 3 (194,640,791 to 194,672,463, reverse strand). Ensembl gene ENSG00000041802.
Subcellular location: Cytoplasm; Endoplasmic reticulum; Nucleus, Cajal body
Subcellular location (Human Protein Atlas): Cytosol; Nuclear bodies; Nucleoplasm
Gene Ontology:
Molecular function: GTP binding; GTPase activity
Biological process: nuclear export; ribosomal subunit export from nucleus
Cellular component: Cajal body; cytoplasm; cytosol; endoplasmic reticulum; membrane; nuclear body; nucleoplasm
Genetic constraint (gnomAD): Loss-of-function variants: 51 observed, 76.4 expected, observed/expected ratio (o/e) 0.67, 90% interval 0.53 to 0.84. The upper end of that interval is the gene's LOEUF score, 0.84, which puts it in group 3 of 6, group 1 being the genes least tolerant of losing a copy. Missense variants: 775 observed, 806.08 expected, observed/expected ratio (o/e) 0.96, 90% interval 0.91 to 1.02. Synonymous variants: 257 observed, 285.44 expected, observed/expected ratio (o/e) 0.9, 90% interval 0.81 to 1.
Homologues: Orthologues: chimpanzee LSG1 (98% identical), macaque LSG1 (95% identical), rabbit LSG1 (86% identical), pig LSG1 (85% identical), dog LSG1 (83% identical), rat Lsg1 (82% identical), mouse Lsg1 (82% identical), zebrafish lsg1 (66% identical), tropical clawed frog lsg1 (59% identical), Drosophila melanogaster Ns3 (46% identical), Caenorhabditis elegans C53H9.2 (37% identical). Paralogues in human: GNL1 (21% identical), GNL3L (18% identical), GNL2 (17% identical), GNL3 (15% identical), NOA1 (12% identical), MTG1 (10% identical).
Diseases named in the same sentence as LSG1 in open-access papers:
LSG1 is named in the same sentence as 6 diseases in open-access papers, as found by Europe PMC text mining. Sharing a sentence is not in itself a finding about the gene and the disease. The quoted sentences say what the papers report.
clear cell renal cell carcinoma (2 papers, 2022 to 2024). "A previous study found that METTL14 was down-regulated in the clear cell renal cell carcinoma (ccRCC) tissues, and the m6A level of Lnc-LSG1 could be regulated by METTL14, thereby playing important roles in ccRCC progression." (PMID 38326804, 2024).
cervical cancer (1 paper, 2017). A primary or metastatic malignant neoplasm involving the cervix. "LSG1 has not been described to be associated with cervical cancer." (PMID 29312619, 2017).
cancer (1 paper, 2019). A tumor composed of atypical neoplastic, often pleomorphic cells that invade other tissues. "Inhibition of eEF2 is toxic to mammalian cells due to inhibition of translation, but here, we demonstrate that inhibition of LSG1, and possibly EFL1 by extension, may provide an effective prosenescent cancer therapy with lesser side effects since translation remains unimpaired." (PMID 31148378, 2019).
infection (1 paper, 2019). The state of being infected such as from the introduction of a foreign agent such as serum, vaccine, antigenic substance or organism. "Infection of cells with a lentiviral vector encoding a shRNA to LSG1 led to efficient knockdown of the protein, as assessed by Western blot." (PMID 31148378, 2019).
LSG1 also shares sentences with these, for which no sentence is quoted: heart failure (1 paper); tumour (1).